ACCS (1-aminocyclopropane-1-carboxylate synthase homolog (inactive))
Description:
Does not catalyze the synthesis of 1-aminocyclopropane-1-carboxylate but is capable of catalyzing the deamination of L-vinylglycine.
Synonyms: PHACS; ACS
Tractability: No criterion of Open Targets' tractability assessment is met for any kind of drug.
Gene: Protein-coding gene on chromosome 11 (44,065,916 to 44,084,241, forward strand). Ensembl gene ENSG00000110455.
Subcellular location (Human Protein Atlas): Golgi apparatus
Gene Ontology:
Molecular function: 1-aminocyclopropane-1-carboxylate synthase activity; identical protein binding; protein binding; pyridoxal phosphate binding
Genetic constraint (gnomAD): Loss-of-function variants: 44 observed, 62.94 expected, observed/expected ratio (o/e) 0.7, 90% interval 0.55 to 0.9. The upper end of that interval is the gene's LOEUF score, 0.9, which puts it in group 3 of 6, group 1 being the genes least tolerant of losing a copy. Missense variants: 602 observed, 657.55 expected, observed/expected ratio (o/e) 0.92, 90% interval 0.86 to 0.98. Synonymous variants: 230 observed, 250.93 expected, observed/expected ratio (o/e) 0.92, 90% interval 0.82 to 1.02.
Homologues: Orthologues: mouse Accs (83% identical), guinea pig ACCS (82% identical), pig ACCS (81% identical), rat Accsl (81% identical), zebrafish accs (52% identical), Caenorhabditis elegans nkat-3 (15% identical), Drosophila melanogaster CG1640 (15% identical), Drosophila melanogaster CG6321 (14% identical), Caenorhabditis elegans nkat-1 (13% identical), Caenorhabditis elegans C32F10.8 (13% identical). Paralogues in human: ACCSL (49% identical), GPT (17% identical), AADAT (16% identical), GPT2 (16% identical), TAT (15% identical), KYAT1 (15% identical), KYAT3 (15% identical).
Diseases named in the same sentence as ACCS in open-access papers:
ACCS is named in the same sentence as 11 diseases in open-access papers, as found by Europe PMC text mining. Sharing a sentence is not in itself a finding about the gene and the disease. The quoted sentences say what the papers report.
adrenal neoplasms (1 paper, 2024). "We have used a fully automated technology that measures the cross-sectional area at various levels (L1–L5) and shown that there is indeed profound loss in muscle mass at diverse levels compared to non-functional ACCs and other adrenal neoplasms." (PMID 38806535, 2024).
cyst (1 paper, 2018). A sac-like closed membranous structure that may be empty or contain fluid or amorphous material. "Analysis based on gene knockdown technology may provide an enhanced understanding of the roles of key enzymes, namely AcGDH, AcSPAT or AcCS, during cyst formation." (PMID 30477573, 2018).
diabetes (1 paper, 2024). "Therefore, inflammation in diabetes is the plausible and acceptable cause of increased levels of the proteins ACCS, GCSF, and SMAD4." (PMID 39335530, 2024). "Depending on the low-grade inflammatory nature of diabetes, we investigated three proteins in T2DM patients: 1-aminocyclopropane-1-carboxylate synthase (ACCS), granulocyte–colony-stimulating factor (G-CSF), and Sma Mothers Against Decapentaplegic homolog-4 (SMAD4)." (PMID 39335530, 2024). "However, the role of ACCS in diabetes has not yet been studied." (PMID 39335530, 2024).
hyperandrogenism (1 paper, 2016). Excessive secretion of androgens from the adrenal glands or gonads. "In the seven female patients with isolated hyperandrogenism, age at diagnosis was lower in patients with hypercortisolism (alone or in association with androgen issues) and those with non-functioning ACCs." (PMID 27504106, 2016).
Multiple osteochondromas (1 paper, 2012). Multiple osteochondromas (MO) is characterised by development of two or more cartilage capped bony outgrowths (osteochondromas) of the long bones. "ACCS:EXT2 (#9) - EXT2 is a tumour supressor gene implicated in multiple osteochondroma, with the gene being affected by a wide-range of mutations including frameshift and splice-site mutations." (PMID 22761941, 2012).
pancreatic cancer (1 paper, 2023). "In the current study, a total of 17 genes with prognostic values have been identified, of which 8 genes (SFXN5, LRRC8E, KCNJ10, UPB1, SLC43A2, SLC38A10, ACCS, and SLC38A5) were identified for the first time in pancreatic cancer." (PMID 37333498, 2023).
tumour (2 papers, 2012 to 2024). "In 60% of cases, ACCs are hormonally functional tumours that usually secrete cortisol, but the secretion of oestrogen, androgens, and mineralocorticoids is well documented." (PMID 38337539, 2024).
cancer (1 paper, 2024). A tumor composed of atypical neoplastic, often pleomorphic cells that invade other tissues. "The role of ACCs in cancer is receiving increased interest due to their involvement in lipid metabolism, providing cancer cells with essential building blocks for rapid proliferation and survival, particularly in lipogenic cancers such as breast, prostate and liver cancer." (PMID 39136185, 2024).
ACCS also shares sentences with these, for which no sentence is quoted: adenoid cystic carcinoma (1 paper); hypercortisolism (1); Hyperglycemia (1).